VIM (vimentin)
Diseases named in the same sentence as VIM in open-access papers (continued):
Sharing a sentence is not in itself a finding about the gene and the disease.
cardiomyopathy (3 papers, 2021 to 2022). A disease of the heart muscle or myocardium proper. "Our data show a significant relationship between secreted levels of vimentin, 8-OHdG, and endostatin with decreased EF and increased diastolic diameter in CD patients and offer new blood biomarkers to predict the risk of cardiomyopathy, HF, and adverse outcomes in CD patients." (PMID 34479416, 2021). "Vimentin is commonly recognised as a marker of activated myofibroblasts involved in cardiomyopathy, and several studies have uncovered its cardioprotective effects in cardiomyocytes." (PMID 34966794, 2021).
cervical dysplasia (3 papers, 2016 to 2025). "To evaluate CAF accumulation during cervical carcinogenesis, we detected α-SMA (CAF marker), fibroblast activation protein (FAP) (CAF marker), and Vimentin (fibroblast maker) levels in different grades of cervical dysplasia and CC." (PMID 33731705, 2021). "Expression levels of Sec62 and vimentin were analyzed in liquid based cytology specimens from 107 women with varying grades of cervical dysplasia ranging from normal cases to cancer by immunofluorescence cytology." (PMID 27553742, 2016).
colorectal adenoma (3 papers, 2017 to 2025). An adenoma that arises from the colon or rectum. "Proteomics of colorectal adenomas of FAP patients showed that the vimentin upregulation and hemoglobin subunit beta downregulation distinguished the FAP patients in two groups with high vs. low residual 11-dehydro-TXB2 levels, possibly identifying Aspirin nonresponders and responders, respectively." (PMID 37173923, 2023).
diabetic retinopathy (3 papers, 2016 to 2022). "GFAP and vimentin, related to diabetic retinopathy and stress, were the lowest for the case of 160 μW treatment at the value of 2.607 and 0.909." (PMID 35092362, 2022). "Snail, N-cadherin, Vimentin, β-catenin, and α-smooth muscle actin (α-SMA) levels were all dramatically increased in retinas from humans with diabetic retinopathy (DR) and from DR mouse models." (PMID 27999189, 2017). "In addition, vimentin and GFAP, related to diabetic retinopathy and retina stress, were significantly decreased in the treated group with the far red/NIR LED contact lens compared to the untreated group." (PMID 35092362, 2022).
diffuse large B-cell lymphoma (3 papers, 2013 to 2024). "Vimentin was also identified as a mediator of drug-resistant phenotype in diffuse large B-cell lymphoma." (PMID 39123440, 2024). "Vimentin mediate a drug-resistant invasive phenotype in diffuse large B cell lymphoma." (PMID 23128467, 2013).
E. coli (3 papers, 2012 to 2021). "Of note is that VIM deficiency in mouse-based disease models reduces inflammation, including absent inflammasome activation in the brain after EV-A71 infection and enhanced production of reactive oxygen species by activated macrophages in the gut after Escherichia coli infection." (PMID 34571970, 2021). "In summary, the current studies with IbeA+ E. coli K1 infection in HBMECs show that vimentin and PSF play an important role in the pathogenesis of meningitic infection by contributing to modulation of the early and late events of NF-κB signaling in a coordinated manner." (PMID 22536447, 2012).
embryonal sarcoma (3 papers, 2007 to 2022). "UESLs are usually diffusely positive for vimentin and a1-antitrypsin and focally positive for cytokeratin, desmin, α-SMA, muscle-specific actin, CD68, myoglobin, neuron-specific enolase, S100, and CD34, suggesting that an embryonal sarcoma is undifferentiated." (PMID 36107353, 2022).
encephalitis (3 papers, 2013 to 2020). An acute inflammatory process affecting the brain parenchyma. "In addition, irregular distribution of vimentin in astrocyte cells could affect their biochemical support of endothelial cells, thus destroying the blood brain barrier, and leading to encephalitis." (PMID 24073199, 2013). "Further investigations of the role of vimentin and cytopathogenesis in JEV-infected NPCs will improve our understanding of the viral-cellular interactions and may help us to design effective treatments for acute viral encephalitis and persistent infection in the infected patients." (PMID 25517725, 2014).
endocervical carcinoma (3 papers, 2006 to 2024). A carcinoma that arises from epithelial cells of the endocervix. "Additionally, vimentin protein expression is already an attractive biomarker as it is routinely used in many pathology labs to distinguish between endometrial and endocervical cancer." (PMID 39516342, 2024).
endometrial tumors (3 papers, 2015 to 2024). "To further explore the vimentin expression in endometrial tumors, we investigated VIM mRNA expression in an independent gene expression dataset from our population-based cohort (n = 254)." (PMID 37146405, 2023). "Immunohistochemistry, as well, confirmed a primary endometrial tumour with negativity for GCDFP-15, CEA, CDX2, CK20; and positivity for CK7, ER, and Vimentin." (PMID 26682077, 2015). "Furthermore, treatment of Lkb1fl/flp53fl/fl transgenic mice with linoleic acid for four weeks significantly reduced the growth of endometrial tumors and decreased the expression of VEGF, vimentin, Ki67, and cyclin D1 in tumor tissues." (PMID 38465855, 2024). "We report that low-stage endometrial tumors that later recurred show lower epithelial vimentin expression than tumors that did not recur." (PMID 37146405, 2023).
epithelioid angiosarcoma (3 papers, 2013 to 2024). "CD31, ERG, vimentin, factor VIII-related antigen, and Ulex europaeus agglutinin-1 (UEA-1) are sensitive and reliable markers for the immunohistochemical evaluation of epithelioid angiosarcoma." (PMID 35224706, 2022). "Coexpression of mesenchymal (vimentin) and endothelial (particularly CD31 and Fli-1) markers along with epithelioid histopathological features confirms diagnosis of epithelioid angiosarcoma." (PMID 23844302, 2013).
hepatoblastoma (3 papers, 2013 to 2024). Hepatoblastoma (HB) is a malignant hepatic tumor and is the most common pediatric liver cancer. "Previously, we identified a CSC population in hepatoblastoma cell lines expressing the CSC markers CD34 and CD90, cell surface Vimentin (csVimentin) and binding of OV-6." (PMID 36497307, 2022).
histiocytic sarcoma (3 papers, 2022 to 2025). An aggressive malignant neoplasm with a poor response to therapy, usually presenting as stage III/IV disease. "Previously, immunohistochemical markers used for histiocytic sarcomas in rats included vimentin, CD68 and lysozyme." (PMID 35454212, 2022). "Vimentin expression has been observed in tissues of patients with various histiocytic disorders, including LCH, histiocytic sarcoma (HS), interdigitating dendritic cell sarcoma (IDCS) and multicentric reticulohistiocytosis (MR)." (PMID 38342891, 2024). "In Mongolian gerbils, there were two cases of abdominal scent gland epithelioma (both two-year-old males) and one case of histiocytic sarcoma located in the nasal area (age unknown, female; tumour cells expressed Iba-1 and vimentin, clone V9, and were negative for desmin and α-SMA-)." (PMID 35454212, 2022).
HIV-1 infection (3 papers, 2016 to 2023). The type species of lentivirus and the etiologic agent of acquired immunodeficiency syndrome (AIDS). "The involvement of vimentin in HIV-1 infection has been suggested by a previous study, in which vimentin knockdown suppressed HIV-1 replication in MT4 cells." (PMID 37376566, 2023). "In this study, we explored the role of vimentin in HIV-1 infection." (PMID 37376566, 2023). "HIV-1 infection was impaired in the vimentin-knockout cells." (PMID 37376566, 2023). "That premise led us to hypothesize that it would be possible to inhibit HIV-1 infection by modulating cellular vimentin IFs, either through a reduction in vimentin levels or by inducing structural changes in IFs." (PMID 27314381, 2016). "Without the local accumulation of CD4, HIV-1 infection may be insufficient, as observed in the HIV-1 infection of vimentin-deficient cells." (PMID 37376566, 2023).
in situ carcinoma (3 papers, 2014 to 2024). A malignant epithelial neoplasm which is confined to the epithelial layer without evidence of further tissue invasion. "First, we examined the expression of EMT markers (E-cadherin, β-catenin, and vimentin) in invasive LSCC (n = 20), adjacent in-situ carcinoma (n = 9), and normal epithelium (n = 10)." (PMID 31885577, 2019).
influenza (3 papers, 2022 to 2024). An acute viral infection of the respiratory tract, occurring in isolated cases, in epidemics, or in pandemics; it is caused by serologically different strains of viruses (influenzaviruses) designated A, B, and C, has a 3-day incubation period, and usually lasts for 3 to 10 days. "We confirmed both cit-vimentin and influenza NP were endocytosed by HLA class I-expressing CD11c+ antigen-presenting cells (APCs)." (PMID 36658110, 2023). "No decrease in frequency was seen over time for influenza, cit-fibrinogen-β/vimentin or cit-α-enolase/CILP-specific cells in any of the groups." (PMID 39557489, 2024). "We also subjected four known epitopes to the same scoring protocol: the PADRE epitope (AKFVAAWTLKAAA), an influenza immunogenic epitope (PKYVKQNTLKLAT), the Vimentin peptide (SAVRLRSSVPGVR) and the natural CLIP substrate (PVSKMRMATPLLMQA), which were used as controls." (PMID 35572587, 2022).
intestinal tumor (3 papers, 2015 to 2024). "Epithelial mesenchymal transition (EMT) in human intestinal tumor progression is associated with the upregulation of the intermediate filament protein vimentin." (PMID 32765634, 2020). "To validate the impact of MLCD on AOM/DSS-induced EMT in the intestinal tumor tissues of C57BL/6 mice, we assessed the protein and mRNA expression levels of three primary components involved in the EMT process—vimentin, N-cadherin, and E-cadherin—using WB and qRT‒PCR." (PMID 38710918, 2024). "Therefore, we examined the expression of vimentin (an EMT marker) in E-cadherin down-regulated cells and intestinal tumor tissues by Western blotting." (PMID 25605242, 2015).
lymphedema (3 papers, 2020 to 2024). Excess fluid collection in tissues, causing swelling. "Vimentin-positive cells in fibrotic lesions of lymphedema patients were diffusely scattered in the adipose tissue, whereas a few α-SMA-positive cells were found in the serial sections alongside vimentin staining." (PMID 37886950, 2023). "Additionally, the results of vimentin, PDGF-A immunostaining, and toluidine blue staining on serial sections of adipose tissue from lymphedema patients revealed that MCT cells housed secretory granules that reacted positively to the anti-PDGF-A antibody." (PMID 37886950, 2023). "Furthermore, vimentin and PDGF-A immunostaining of serial sections of adipose tissue obtained from lymphedema patients showed that MCT-type MCs contained secretory granules stained with the anti–PDGF-A antibody." (PMID 37886950, 2023). "Furthermore, vimentin and PDGF-A immunostaining performed on serial sections of adipose tissue obtained from lymphedema patients showed that MCT-type MCs contained secretory granules stained with anti-PDGF-A antibody." (PMID 37886950, 2023).
malignant mesothelioma (3 papers, 2011 to 2021). A malignant neoplasm of the pleura or peritoneum, arising from mesothelial cells. "Histopathological classification of tumors and, additionally, immunohistochemistry were conducted for podoplanin, pan-cytokeratin, and vimentin to compare induced tumors with malignant mesotheliomas occurring in humans." (PMID 25410479, 2014). "All biphasic-type malignant mesotheliomas were immunohistochemically positive for the markers vimentin, podoplanin, and pan-cytokeratin." (PMID 25410479, 2014). "All sarcomatoid-type malignant mesotheliomas were immunohistochemically positive for the markers vimentin and podoplanin." (PMID 25410479, 2014). "All epithelioid-type malignant mesotheliomas were immunohistochemically positive for the markers pan-cytokeratin, podoplanin, and vimentin." (PMID 25410479, 2014). "Malignant mesotheliomas have no characteristic paranuclear dot-like expressions of desmin and vimentin." (PMID 34193155, 2021).
malignant pleural mesothelioma (3 papers, 2019 to 2020). A malignant neoplasm that arises from mesothelial cells in the pleura and shows a diffuse growth pattern. "It has been reported overexpressed let-7b activating epithelial marker E-cadherin and attenuating mesenchymal marker Vimentin, EMT transcriptional factor Twist as well as β-catenin in malignant pleural mesothelioma." (PMID 32650795, 2020).
metabolic syndrome (3 papers, 2021 to 2024). A cluster of metabolic risk factors for CARDIOVASCULAR DISEASES and TYPE 2 DIABETES MELLITUS. "Seven metabolic syndrome-related genes (CSF3R, TMEM132A, STAB1, VIM, DUOXA1, PILRB, and SLC2A4) were used to construct risk equations." (PMID 37033267, 2023).
myocardial infarction (3 papers, 2022 to 2023). Gross necrosis of the myocardium, as a result of interruption of the blood supply to the area, as in coronary thrombosis. "It was found that FBs were proliferated in the site of myocardial infarction and Actn2 was colocalized with Vimentin." (PMID 35203611, 2022). "S100A8, S100A9 40, 41, and vimentin 42 are recognized as DAMPs in myocardial infarction (MI) and atherosclerosis." (PMID 35173530, 2022).
myofibroblastoma (3 papers, 2016 to 2023). A benign, well circumscribed soft tissue neoplasm characterized by the presence of spindle shaped myofibroblasts and mast cells in a collagenous stroma. "Intranodal schwannoma were often positive for vimentin and S100, which are similar with myofibroblastomas, and negative for SMA and CD34, which are not similar with myofibroblastomas." (PMID 26911514, 2016).
Niemann-Pick type C disease (3 papers, 2013 to 2022). "Niemann-Pick type C disease – a severe neurodegenerative disorder with massive accumulation of cholesterol, fatty acids and other hydrophobic substances – showed vimentin hypophosphorylation leading to lipid transport defects." (PMID 24587346, 2014). "To clarify which stage of lipid uptake was affected by vimentin, we used U18666A, a specific inhibitor for NPC-1 (Niemann-Pick disease, type C1)." (PMID 35656400, 2022).
oesophageal cancer (3 papers, 2019 to 2022). "In this study, we describe a case of esophageal carcinoma with undifferentiated components and rhabdoid features that was exclusively positive for vimentin and SMARCB1 and associated with prolonged survival." (PMID 30649642, 2019). "Western blot analysis showed that the levels of MMP9 and vimentin in oesophageal cancer cells treated with apatinib and cytotoxic drugs were significantly decreased, and E‐cadherin expression was increased." (PMID 35315581, 2022). "In this study, we describe a case of esophageal carcinoma with undifferentiated components and rhabdoid features that was exclusively positive for vimentin and SMARCB1 in a patient with prolonged survival." (PMID 30649642, 2019). "The oesophageal cancer cells treated with si‐HOTAIR or miR‐204 mimic exhibited decreased expression levels of HOXC8, Vimentin and MMP‐9, but increased E‐cadherin level." (PMID 31389660, 2019).
oncocytic tumor (3 papers, 2015 to 2025). "About vimentin immunoreactivity, it was variable, but in most of the cases an oncocytic tumor has diffuse positivity for vimentin." (PMID 26989553, 2016). "Vimentin is currently used to differentiate between malignant renal carcinomas and benign oncocytomas." (PMID 25944973, 2015). "The full length molecule of Vimentin is used as a marker to differentiate benign oncocytomas, expected to be negative, from malignant renal cell carcinomas being Vimentin positive." (PMID 25944973, 2015).
osteoarthritis (3 papers, 2017 to 2023). A noninflammatory degenerative joint disease occurring chiefly in older persons, characterized by degeneration of the articular cartilage, hypertrophy of bone at the margins and changes in the synovial membrane. "As a main component of chondrocyte cytoskeleton, vimentin played an important role in maintaining the stiffness of chondrocytes in osteoarthritis." (PMID 36437834, 2022). "ACPAs of CK13 (cCK13), tenascin‐C (cTNC5), vimentin (cVIM), α‐enolase (CEP‐1), and fibrinogen β (cFIBβ) were examined by enzyme‐linked immunosorbent assay in patients with RA (n = 287) and patients with osteoarthritis (n = 330), and cross‐reactivity was assessed by inhibition assays." (PMID 29084415, 2017).
ovarian clear cell cancer (3 papers, 2015 to 2025). An invasive malignant neoplasm that arises from the ovary and is characterized by a predominance of clear and hobnail malignant epithelial cells. "Binding between ANXA4 and Vimentin promotes the proliferation, invasion, and migration of ovarian clear cell carcinoma, and inhibits cell apoptosis by activating the ERK and NF-kB pathways." (PMID 31474227, 2019).
pituicytoma (3 papers, 2016 to 2025). An extremely rare, WHO grade I, circumscribed and slow-growing tumor that arises from the neurohypophysis or infundibulum and described in adults. "Combined with our hospital and previous reports, the results of immunohistochemistry were analyzed as follows: It can be seen that TTF-1, S100 and vimentin were usually positive in pituicytomas, and the positive rates were 100%, 97.7% and 93.7% respectively." (PMID 33982223, 2021). "Generally, pituicytomas are noninfiltrative and immunoreactive for vimentin, S-100 protein, and GFAP (often focally), with occasional cytoplasmic EMA positivity." (PMID 26962837, 2016).
prion disease (3 papers, 2010 to 2022). A transmissible disease that is caused by a protein that is able to induce abnormal folding of normal cellular proteins, leading to characteristic spongiform brain changes, which are associated with neuronal loss without an inflammatory response. "In cellular models of prion disease, intra-neuronal prion propagation in the presence of mild proteasome inhibition triggered formation of cytosolic aggresomes containing vimentin, PrPSc, hsp70, ubiquitin and proteasome subunits." (PMID 26646779, 2016). "In addition, molecular markers of neuroinflammation and particularly indicators of astrocyte and microglia activation [such as vimentin, galectin-1, and glial fibrillary acidic protein (GFAP)] were up-regulated in murine prion disease." (PMID 36378750, 2022).
pterygium (3 papers, 2012 to 2021). A wedge-shaped fibrovascular lesion arising from the bulbar conjunctiva and extending to the cornea. "In fact, abnormal vimentin expressing cells were reported in pterygium tissue." (PMID 24825356, 2014). "Vimentin is a type III intermediate filament, a major cytoskeletal component of mesenchymal cells, and present in cells at the focal areas of a surgical pterygium tissue." (PMID 24825356, 2014). "Nevertheless, Dushku and Reid showed that pterygium originates from altered limbal epithelial basal cells which express vimentin but do not stain for keratins, so our primary cultures seem to represent the characteristic cells of pterygium." (PMID 22724003, 2012).